RNU6-938P (RNA, U6 small nuclear 938, pseudogene)
Gene: Small nuclear RNA gene on chromosome 17 (75,409,086 to 75,409,188, reverse strand). Ensembl gene ENSG00000223217.
Homologues: Orthologues: chimpanzee U6 (98% identical), macaque U6 (95% identical), pig U6 (82% identical), pig U6 (78% identical). Paralogues in human: RNU6-1094P (89% identical), RNU6-797P (88% identical), RNU6-1022P (87% identical), RNU6-454P (87% identical), RNU6-1047P (86% identical), RNU6-923P (86% identical), RNU6-1159P (85% identical), RNU6-115P (85% identical), RNU6-1209P (85% identical), RNU6-1243P (85% identical), RNU6-130P (85% identical), RNU6-16P (85% identical), and 1284 more.